AHR (aryl hydrocarbon receptor)
Diseases named in the same sentence as AHR in open-access papers (continued):
Sharing a sentence is not in itself a finding about the gene and the disease.
psoriasis (103 papers, 2014 to 2026). An autoimmune condition characterized by red, well-delineated plaques with silvery scales that are usually on the extensor surfaces and scalp. "Such targeted therapies hold promise for effectively preventing and treating inflammatory skin diseases such as AD and psoriasis while minimizing adverse effects associated with AhR activation in immune cells." (PMID 39939818, 2025). "AhR is implicated in psoriasis, particularly in regulating the immune balance of Th17/22 and Treg cells." (PMID 38892253, 2024). "Another molecular mechanism linked to inflammatory processes in psoriasis is dysregulation of the AHR pathway." (PMID 39337637, 2024). "In an IMQ-induced psoriasis model, AhR deficiency played a key role in exacerbating skin inflammation (including in keratinocytes) with nonhematopoietic cells." (PMID 38892253, 2024). "Certain AHR mutations which lead to overstimulation of the receptor seem to correlate with psoriasis susceptibility." (PMID 39337637, 2024). "Exposure to air pollutants such as PAHs, particulate matter, and volatile organic compounds activates the aryl hydrocarbon receptor and further activates Th17 cells, serving as the most critical cells implicated in the pathogenetic mechanism of psoriasis." (PMID 39058174, 2024). "In a study of AHR-deficient mouse models, the mice demonstrated increased IL-22 and IL-17 cytokines, as well as psoriasis-like skin inflammation." (PMID 39337637, 2024). "Many protein products of epidermal differentiation encoded by EDC genes are differentially affected in AD and psoriasis via the AhR pathway." (PMID 37573390, 2023). "In a model of imiquimod-induced psoriasis, AhR-deficient mice had exacerbated skin inflammation, while topical application of the AhR agonists FICZ or Tapinarof ameliorated disease symptoms." (PMID 37190854, 2023). "Activation of this AhR signaling pathway in epidermal keratinocytes initiates inflammatory skin lesions and has been implicated in inflammatory diseases such as psoriasis and AD." (PMID 37623895, 2023). "AhR‐deficient mice experienced marked psoriasiform skin inflammation with elevated IL‐17 and IL‐22 production in an imiquimod‐induced psoriasis model compared to controls." (PMID 36226669, 2022). "In conclusion, the AhR agonist TCDD increases pro-inflammatory cytokines associated with psoriasis skin tissue through activation of the AhRR/NF-κB signaling pathway." (PMID 34884515, 2021). "Disorders whose pathomechanism is associated with AhR function in the skin include, among others, chloracne, hyperpigmentation, and vitiligo, as well as inflammatory diseases such as psoriasis or atopic dermatitis." (PMID 33499346, 2021). "AhR ligands, such as coal tar, FICZ and tapinarof via the AhR pathway, restore barrier dysfunction and have been implicated into atopic dermatitis or psoriasis therapy." (PMID 32899152, 2020). "In an imiquimod-induced psoriasis model, AhR deficiency exacerbates skin inflammation with upregulated gene expression of Il22, Il17a, and Il23." (PMID 31683543, 2019). "A strong association between the AhR/ NFκB axis and the inflammatory response in psoriasis." (PMID 39465158, 2024). "Dysregulation of AHR by either genetic deficiency or by excess activity of the downstream negative regulator Cyp1a1 causes skin pathology, and patients suffering from psoriasis display reduced activity of the AHR pathway and increased enzymatic activity of Cyp1a1 compared with healthy donors." (PMID 39242971, 2024). "In an imiquimod-induced psoriasis model, AHR deficiency increases inflammation of skin." (PMID 38907248, 2024). "The AhR tryptophan signaling pathway has been implicated in psoriasis, much like in AD." (PMID 37623895, 2023). "The role of AhR, a ligand-activated transcription factor involved in immune regulation and inflammation, is closely linked to chronic inflammatory skin diseases like AD and psoriasis." (PMID 37573390, 2023).
psoriasis (continued). "AhR is known to be associated with diseases in various organs; however, its functions in chronic inflammatory skin diseases, such as atopic dermatitis (AD) and psoriasis (PS), have recently been elucidated." (PMID 35625824, 2022). "In addition, an increase in mRNA expression of several proinflammatory cytokines involved in psoriasis, such as Il 17a, Il 17c, Il 23, Il 22, and Il 1b, was observed in the skin lesions of AHR-deficient mice." (PMID 33499346, 2021). "IEL function, release of cytokines and antimicrobial factors, depends on the expression of GLP-1R, its absence resulting in dysregulated intestinal gene expression, an altered microbiota composition, and enhanced sensitivity to colitis, similar to AhR-deficiency with a link to psoriasis." (PMID 31379871, 2019). "Moreover, the recent identification of psoriasis susceptibility SNPs near the AHR locus not only lends further support to the importance of AHR in psoriasis pathogenesis but also raises the possibility of genetically driven influences on AHR expression." (PMID 40004095, 2025). "Importantly, our study is the first to demonstrate that IDG significantly improves the severity of IMQ-induced psoriasis-like skin lesions in mice and to establish that the mechanism underlying this effect may involve the AHR and NFκB signaling pathways." (PMID 39465158, 2024). "Increased AhR expression has been demonstrated in skin biopsy samples of patients with PS, and treatment of skin cells with AhR ligands in vitro results in the modulation of genes, including IL-6, IL-8, and type I and II interferon pathway genes implicated in the pathogenesis of psoriasis." (PMID 35625824, 2022). "A previous study investigating the AhR-CYP signaling pathway in patients with exacerbated psoriasis reported a significant increase in serum CYP1A1 expression." (PMID 40864793, 2025). "As for psoriasis, a deep investigation of the AHR pathway in AD is needed to clarify the current discrepancies, better understand the complex regulation of the pathway, and potentially identify novel therapeutic targets." (PMID 40004095, 2025). "This aligns with previous studies reporting decreased AhR expression in other inflammatory skin disorders, including psoriasis, atopic dermatitis, acne, hidradenitis suppurativa, and vitiligo." (PMID 40162433, 2025). "In psoriasis, the transcription factors Nuclear Factor Kappa B (NF-κB) and Aryl Hydrocarbon Receptor (AhR) play key roles in regulating inflammatory pathways." (PMID 40343299, 2025). "Three studies report increased AHR transcript and protein expression in psoriasis lesional versus healthy skin." (PMID 40004095, 2025). "We have also detected decreased AHR mRNA expression in psoriasis lesional as compared to healthy skin, as well as in whole blood, in our ongoing investigation of the AHR pathway in skin inflammation." (PMID 40004095, 2025). "Further mechanistic studies revealed that metabolites influence psoriasis progression through the AhR pathway, including effects on intestinal and skin barrier integrity, as well as immune cell regulation." (PMID 41425939, 2025). "How to reconcile these discrepancies and how these findings relate to the beneficial role of AHR activation in psoriasis remains to be clarified." (PMID 40004095, 2025). "Specifically, the AhR agonist tapinarof has recently been approved by the FDA as a first-of-its-kind topical drug for psoriasis and is in clinical trials for AD." (PMID 39939818, 2025). "The aryl hydrocarbon receptor (AhR) is a crucial modulator of inflammation, as seen in psoriasis models, where its activation reduces inflammation, whereas its absence exacerbates disease." (PMID 39229121, 2025). "Previous reports have shown that substances such as medicinal coal tar and soybean tar glyteer have therapeutic effects on inflammatory dermatitis such as AD and psoriasis through regulating oxidative stress by activating AhR." (PMID 41229709, 2025).
psoriasis (continued). "In summary, this study demonstrated that OMT inhibits Malassezia biofilm formation and ameliorates Malassezia-associated psoriasis by modulating oxidative stress, inflammation, and apoptosis via STAT3/Nf-κB and AhR/Nrf2 pathways." (PMID 41878517, 2025). "Tapinarof is a first-in-class AhR approved by the FDA for the treatment of psoriasis, and it is currently being investigated for the treatment of atopic dermatitis as well." (PMID 40574044, 2025). "AhR agonists have been approved by the FDA for psoriasis treatment and are in clinical trials for the treatment of atopic dermatitis (AD), but the underlying mechanism of action remains poorly defined." (PMID 39939818, 2025). "Some new drugs, such as tapinarof for psoriasis, are designed to target AhR as their primary therapeutic mechanism for modulating the immune response." (PMID 41440753, 2025). "Activation of this receptor by the recently approved topical AHR-modulating agent Tapinarof effectively controls psoriasis symptoms." (PMID 40021644, 2025). "Tapinarof is a small‐molecule aryl hydrocarbon receptor (AhR) agonist clinically used to treat psoriasis and atopic dermatitis." (PMID 40159643, 2025). "While some of AhR’s functions in psoriasis have been validated, further research is required to fully understand the molecular mechanisms by which AhR regulates skin homeostasis during inflammatory responses." (PMID 41425939, 2025). "These factors promote cross talk between AhR and the Nrf2 pathway via flavonoids, which act as pivotal modulators of skin diseases, including psoriasis and AD." (PMID 41229709, 2025). "Another study analysing publicly available microarray data also reports increased AHR mRNA expression in psoriasis lesional compared to matched psoriasis perilesional skin, but there is no direct comparison with healthy skin." (PMID 40004095, 2025). "Indole derivatives, as endogenous ligands of the AHR, activate AHR signaling and alleviate psoriasis and certain dermatitis conditions." (PMID 40703229, 2025). "AhR modulates skin barrier function and inflammatory responses, making it a promising therapeutic target for psoriasis." (PMID 39188726, 2024). "Reaching a balance between under expression and overstimulation of the AHR pathway appears to be key for the management of psoriasis." (PMID 39337637, 2024). "The research on the correlation between air pollution and the progression of psoriasis has primarily focused on the aryl hydrocarbon receptor (AhR) pathway, oxidative stress pathway, genetic pathways, and the subsequent immunological effects." (PMID 39636940, 2024). "The involvement of both the AhR and NF-κB pathways in psoriasis highlights their essential role in disease progression." (PMID 39465158, 2024). "Currently, only Tapinarof topical cream, an AHR agonist, has reached phase 3 trials, and it is being tested for limited indications such as psoriasis and atopic dermatitis." (PMID 39125717, 2024). "Recent advances in our knowledge of psoriasis pathogenesis have led to the development of targeted topical molecules, mostly focused on intracellular signaling pathways such as AhR, PDE-4, and Jak-STAT." (PMID 38399292, 2024). "The aryl hydrocarbon receptor (AHR) is a transcription factor expressed in keratinocyte and was suggested to have a significant relationship to psoriasis." (PMID 38907248, 2024). "It presents molecular targets such as high-mobility group box-1 (HMGB1), dual-specificity phosphatase-1 (DUSP1), and the aryl hydrocarbon receptor (AhR) for treating psoriasis." (PMID 38892253, 2024). "Stimulating AHR activity with the topical AHR agonist Tapinarof has shown clinical efficacy in treating other inflammatory skin diseases such as psoriasis and atopic dermatitis." (PMID 39337637, 2024). "Although research on the interplay between AhR and NF-κB signaling in psoriasis is still limited, both pathways have demonstrated significant potential in suppressing psoriasis-related inflammation." (PMID 39465158, 2024).
psoriasis (continued). "The effect of tapinarof in psoriasis is related to the activation of the aryl hydrocarbon receptor (AhR), a ligand-dependent transcription factor that regulates gene expression in a variety of cells, including immune and epithelial cells." (PMID 39590031, 2024). "Recent advances in our knowledge of psoriasis pathogenesis have also led to the development of targeted topical molecules, mostly focused on intracellular signaling pathways such as AhR, PDE-4, and Jak-STAT." (PMID 38399292, 2024). "The activation of the AhR has been well-established as an effective treatment strategy for psoriasis." (PMID 39465158, 2024). "In psoriasis patients and mouse psoriasis models, Th17 cells highly express AhR, and IL-22 production by Th17 cells has been found to be dependent on AhR." (PMID 39296901, 2024). "The recent licensing of Tapinarof, a topical agent targeting the aryl hydrocarbon receptor (AhR), represents a significant advancement in psoriasis treatment." (PMID 39188726, 2024). "In 2019, Tapinarof (1% benvitimod cream), a natural AHR agonist, was officially approved by the Chinese government for the treatment of psoriasis following successful clinical trials in China (Furue, Hashimoto-Hachiya & Tsuji, 2019)." (PMID 39465158, 2024). "AhR, a ligand-activated cytoplasmic transcription factor, plays a significant role in the treatment of psoriasis." (PMID 39465158, 2024). "On the other hand, PAH-containing coal tar has therapeutic benefits in treating AD and psoriasis, suggesting that AhR activation can be beneficial for treating some existing cutaneous symptoms." (PMID 36767891, 2023). "AhR plays critical roles in inflammatory and immune-mediated cutaneous diseases, including chloracne, atopic dermatitis, and psoriasis." (PMID 38288335, 2023). "Against this background, this review outlines the latest findings on the regulatory mechanisms of the IL-33–IL-37 axis by AHR in AD and psoriasis." (PMID 37834081, 2023). "It has also been shown that the aryl hydrocarbon receptor (AHR), a receptor for dioxins, is involved in the pathogenesis of inflammatory skin diseases such as atopic dermatitis (AD), psoriasis, hidradenitis suppurativa (HS), and acne." (PMID 37834081, 2023). "There have recently been many reports that AhR activation can suppress inflammatory skin conditions, such as atopic dermatitis and psoriasis, and these reports seem to contradict the findings of our study." (PMID 37373144, 2023). "Amino acid and tryptophan sensing are also altered, including the aryl hydrocarbon receptor, as seen in both AD and psoriasis." (PMID 37623895, 2023). "The particular linking and stimulation of AhR a is credited with tapinarof's ability to treat psoriasis." (PMID 37965393, 2023). "Aryl hydrocarbon receptor (AHR)-dependent responses were also evaluated in CD69-deficient mice in a model of psoriasis induced by IL-23, as these mice developed mild psoriasis and showed reduced IL-22 and STAT3 levels." (PMID 37223078, 2023). "6-formylindolo[3,2-b]carbazole (FICZ) is a ligand of AhR that is known to reduce inflammatory responses in skin lesions and psoriasis." (PMID 37623895, 2023). "Growing evidence suggests that exposure to TCDD or BaP induces pathological responses in the skin, leading to chronic inflammatory skin diseases such as psoriasis through AhR activation." (PMID 38288335, 2023). "Specifically, tapinarof is a potential new topical treatment for AD and psoriasis as a therapeutic AHR-modulating agent." (PMID 35663970, 2022). "In recent years, interest in the effects of AhR on psoriasis (PS) and atopic dermatitis (AD) has steadily increased." (PMID 35625824, 2022). "Nonetheless, treatment with tapinarof, a natural AhR agonist, resolved skin inflammation in patients with psoriasis and atopic dermatitis." (PMID 35987825, 2022). "We found that the AHR-mediated IL-37 upregulation attenuates IL-33 expression which is one of the critical cytokines responsible for AD and psoriasis." (PMID 35663970, 2022).
psoriasis (continued). "In psoriasis, Nuclear factor kappa B (NF-κB), and aryl hydrocarbon receptor (AhR) are proved to be the crucial transcription factors for regulating inflammatory pathways." (PMID 35669784, 2022). "Accordingly, we have shown that tapinarof and GFF, which act on AHR, increased the expression of IL-37, which in turn suppressed the expression of IL-33, a crucial cytokine in the development of AD and psoriasis." (PMID 35663970, 2022). "We believe that the AHR/IL-37 axis will be important for future therapeutic strategies for treating AD and psoriasis." (PMID 35663970, 2022). "This article reviews the role of AhR on psoriasis and summarizes the data on the efficacy and safety of tapinarof cream 1% in the treatment of psoriasis." (PMID 36226669, 2022). "Indole derivatives such as IAld, as an endogenous ligand for AHR, have been demonstrated to activate AHR signaling to alleviate psoriasis and AD." (PMID 35887083, 2022). "Currently, agents that act on the AHR for therapeutic purposes (named therapeutic AHR-modulating agents: TAMAs) are being developed for the treatment of AD and psoriasis clinically." (PMID 35663970, 2022). "Towards this end, we review in vivo and in vitro studies on AhR, primarily focusing on psoriasis and atopic dermatitis." (PMID 35625824, 2022). "The topical treatment of lesional skin with AhR agonists demonstrated beneficial effects in AD and psoriasis." (PMID 34299118, 2021). "Conversely, the blocking of AhR signal with the antagonist CH-223191 exacerbates psoriasis gene expression in patient biopsies." (PMID 34944067, 2021). "It was revealed that direct FICZ-mediated AhR activation alleviates inflammation in both human psoriasis samples and a mouse model of psoriasis-like skin lesions." (PMID 33499346, 2021). "In conclusion, we demonstrated that rapamycin alleviates TCDD-induced aggravated dermatitis in mice with imiquimod-induced psoriasis-like dermatitis through AHR and autophagy modulation." (PMID 33921372, 2021). "AhR has been considered as a possible therapeutic target for the treatment of skin diseases such as atopic dermatitis, psoriasis, acne, and vitiligo." (PMID 34163354, 2021). "The interaction between AhR and endogenous ligands changes the inflammatory profile of skin lesions in psoriasis." (PMID 33499346, 2021). "Diverse experimental systems have been used to assess the AHR’s role in skin inflammation, including in vitro assays of keratinocyte stimulation and murine models of psoriasis and atopic dermatitis." (PMID 34831399, 2021). "We previously demonstrated that the AHR agonist TCDD induced inflammation through autophagy inhibition using an in vitro psoriasis keratinocyte model and ex vivo psoriatic skin tissue study, and these findings are consistent with those noted in this study." (PMID 33921372, 2021). "Activation of the AHR pathway downmodulates skin inflammatory responses in animal models and psoriasis clinical samples." (PMID 33385398, 2021). "It has been proposed that AhR/Nrf2 dual activation drives the efficacy of coal tar, a traditional topical treatment for psoriasis and AD that contains complex mixtures of polyaromatic hydrocarbons." (PMID 34944067, 2021). "Evidence regarding the effects of the environmental contaminant TCDD via AHR activation on the pathogenesis of psoriasis has accumulated." (PMID 33921372, 2021). "AhR stimulation is proposed as a therapeutic mechanism for the treatment of psoriasis, and tapinarof is one of the most studied topical drugs." (PMID 34944067, 2021). "Further studies using in vivo models that take into account the immune axis will allow to deepen the biological mechanisms involved in AhR signaling and specially to validate the efficacy of new molecules for the treatment of psoriasis." (PMID 34299118, 2021). "For instance, coal tar attenuates inflammatory response in AD and psoriasis patients by NRF2 activation upon AhR interaction." (PMID 33499346, 2021).